HDAC6 (histone deacetylase 6)
Diseases named in the same sentence as HDAC6 in open-access papers (continued):
Sharing a sentence is not in itself a finding about the gene and the disease.
breast cancer (continued). "To examine the significance of HDAC6 inhibition in breast cancer cell growth, we transiently transfected HDAC6 siRNA into MCF7 cells." (PMID 29113288, 2017). "In this study, we used HDAC6 knockdown and the novel potent and highly selective HDAC6 inhibitor WT161 to characterize the effect of HDAC6 inhibition in breast cancer cells." (PMID 29113288, 2017). "Taken together, these results suggest that WT161-triggered downregulation of EGFR and ERα in breast cancer cells is due to a post-transcriptional and HDAC6-independent event." (PMID 29113288, 2017). "In HER2-positive breast cancer cells, Shp2 also mediates Cdc42 repression, and HDAC6 inhibition or co-suppression of ERK/myosin II promotes normal epithelial lumen phenotype without increasing Cdc42 activity." (PMID 26783207, 2016). "SAHA is a class I HDAC/HDAC6 co-inhibitor and an autophagy inducer currently undergoing clinical investigations in breast cancer patients." (PMID 27065869, 2016). "In breast cancer, HDAC6 mRNA expression is more prevalent in less advanced, less aggressive tumors, and is associated with better prognosis." (PMID 26388610, 2015). "Because Mena forms a complex with Fe65, it is thus possible that Fe65 regulates breast cancer invasion in an acetylation and HDAC6 sensitive manner." (PMID 26166158, 2015). "When the proteasome was inhibited by bortezomib in MCF-7 breast cancer cells, autophagy was induced; when HDAC6 was knocked down, autophagy decreased as well." (PMID 23644884, 2013). "It was shown that specific inhibition of HDAC6 by RNAi resulted in increased radio sensitivity in breast cancer cells." (PMID 22957056, 2012). "HDAC6, an estrogen target gene, expression levels correlate with better prognosis and response to endocrine therapy in breast cancer patients." (PMID 21814622, 2011). "BPA may also depend on Esr1 and HDAC6 to promote breast cancer and may further lead to the activation of oncogene c-Myc in Osteosarcoma." (PMID 41440754, 2025). "In addition, in a study on breast cancer, it was also found that HDAC6 knockdown resulted in reduced LC3B protein and reduced autophagy." (PMID 40260239, 2025). "However, further research is needed to explore the differential roles of HDAC6 in various breast cancer subtypes and to determine the therapeutic potential of selective HDAC6 inhibitors." (PMID 41300448, 2025). "Bioinformatic interrogations point towards an amplification of FH in breast cancer that may reveal an FH dependency that can be targeted with HDAC6 inhibition." (PMID 40721560, 2025). "Moreover, phthalates are suspected to stimulate the proliferation and metastasis of breast cancer cells, promoting tumor progression by upregulating histone deacetylase 6 (HDAC6)." (PMID 38807590, 2024). "Likewise, Nexturastat A was reported to improve the immune checkpoint blockade of antitumor immune response and diminish the aggressiveness of breast cancer cells with minimal cytotoxic effects by specifically targeting HDAC6 in breast cancer." (PMID 38315203, 2024). "In addition, overexpression of HDAC6 in CAFs leads to the infiltration of myeloid-derived suppressor cells and regulatory T cells, which in turn promote breast cancer progression." (PMID 38988323, 2024). "However, there is limited research on the effects and mechanisms of selective HDAC6 inhibitors (HDAC6i), specifically in breast cancer." (PMID 39594707, 2024). "HDAC6 has previously been reported as a deacetylase of HSPA5 in breast cancer cells." (PMID 37696842, 2023). "Cry2 acetylation by p300 and deacetylation by HDAC6 were identified in breast cancer cells." (PMID 37024472, 2023). "This study supports the effects of HDAC6 and p300 in breast cancer; however, we should also recognize that the role of specific KATs in breast cancer might involve the synthetic action of its acetylated substrate." (PMID 37024472, 2023).
breast cancer (continued). "The inhibition of HDAC6 in triple-negative breast cancer cells showed reduced levels of glycolytic metabolites such as PEP, 3-phosphoglyceric acid (3PG), lactate, and pyruvate, confirming the involvement of HDAC6 in regulating glycolysis in breast cancer cells." (PMID 36984785, 2023). "The high expressions of HDAC2 and HDAC6 in mammary carcinomas in female dogs may be useful information for research involving therapeutic targets with iHDACs since their inhibition favors hyperacetylation and transcription of tumor suppressor genes." (PMID 38028583, 2023). "Thus, alpha-tubulin or HDAC6 inhibitors can be potential therapeutic agents for luminal breast cancer." (PMID 35453496, 2022). "HDAC6-regulated breast cancer cell invadopodia formation and invasion activity are also perceived." (PMID 35163593, 2022). "HDAC6 abrogation also reversed TGF-β-mediated EMT in breast cancer cells." (PMID 36457493, 2022). "In addition to HDAC6, several other putative tumor related genes with oncogeneic role in breast cancer were hypermethylated after valeric acid treatment in our study." (PMID 33510252, 2021). "In addition, upregulation of HDAC6 increases cell motility in breast cancer cells, thus contributing to cancer metastasis, whereas in glioblastoma cells genetic silencing of HDAC6 decreases cellular malignancy and reverses the mesenchymal phenotype." (PMID 35008169, 2021). "Increased expression of HDAC1, HDAC2, HDAC3 and HDAC6 are reported in several cancers including colon, prostate and breast cancer and inhibition of HDACs potentially could target proliferation, differentiation, angiogenesis, and migration." (PMID 33802026, 2021). "4-Hydroxybenzoic acid (4-HBA) and a histone deacetylase 6 (HDAC6) inhibitor could successfully reverse adryamicin (ADM) resistance in human breast cancer cells." (PMID 32752302, 2020). "HDAC6 expression has been found to be high in several cancers, including breast cancer." (PMID 31683883, 2019). "However, the expression of HDAC6 in tumor cells has been observed in patients with higher breast cancer survival rates." (PMID 31683808, 2019). "As the result of other studies, HDAC6 has highly expressed in various cancer types including leukemia, prostate carcinoma, colorectal carcinoma and breast cancer compared with normal tissue, and the results also confirmed the high level of HDAC6 in HL-60 and PC-3 cells." (PMID 29593536, 2018). "In this study, we therefore examined whether WT161, a more potent and selective HDAC6 inhibitor, enhances bortezomib-induced cytotoxicity in breast cancer cells." (PMID 29113288, 2017). "Recent studies have examined the biologic role of HDAC6 in cancer cells, including breast cancer." (PMID 29113288, 2017). "Elevated levels of HDAC6 have also been reported in acute myeloid leukemia and some breast cancers." (PMID 26848526, 2016). "In breast cancer cell lines, HDAC6 was shown to be regulated by estrogen." (PMID 26848526, 2016). "Interestingly, breast cancer patients with high level of HDAC6 had a favorable response to anti-estrogen tamoxifen treatment, suggesting a role of HDAC6 in estrogen-induced tumorigenesis." (PMID 26848526, 2016). "However, in breast cancer HDAC6 expression correlates positively to response to endocrine treatment and is inversely related to poor survival and large tumors." (PMID 25915736, 2015). "In addition, HDAC6 depletion-induced block of autophagic flux sensitized breast cancer cells to treatment with the proteasome inhibitor, bortezomib, via decreased autophagic flux." (PMID 25915736, 2015).
breast cancer (continued). "Taking into consideration that HDAC6 plays an important role in progression of human breast cancer, this could explain possible differences between anticancer activity of SAHA/CDDP and VPA/CDDP combinations in triple negative breast cancer cells." (PMID 26580554, 2015). "Additionally, ERα was reported to activate histone deacetylase 6 (HDAC6) to deacetylate tubulins in human breast cancer MCF-7 cells." (PMID 25257666, 2014). "MCF-7 breast cancer cells stimulated with estrogen show up-regulation of HDAC6 gene expression." (PMID 23644884, 2013). "Therefore, tamoxifen, an oestrogen receptor (ER) antagonist, sensitised the cells to apoptosis and death, in which high HDAC6 in breast cancer is considered to be a better prognostic factor, which correlated with higher disease-free survival rate and better endocrine therapy response." (PMID 39941046, 2025). "Notably, multivariate analysis revealed a negative association between HDAC6 and H3K9Ac in neoplastic tissues, suggesting that HDAC6 may play a direct role in H3 deacetylation in canine mammary carcinomas." (PMID 40590021, 2025). "Moreover, HDAC6 has been shown to reduce glycolytic metabolism in breast cancer cells." (PMID 38067315, 2023). "Besides, HDAC6 is highly expressed in estrogen receptor-positive breast cancer cells and accelerates the metastatic process of breast cancer by reducing the acetylation modification of α-tubulin, enhancing microtubule activity, and promoting cell adhesion and migration." (PMID 36457493, 2022). "Therefore, 4-HBA could be applied as an effective HDAC6 inhibitor to reverse human breast cancer resistance." (PMID 32752302, 2020). "For instance, tamoxifen treatment of MCF-7 breast cancer cells prevented estradiol-stimulated HDAC6 accumulation and α-tubulin deacetylation, and nitric oxide (NO) is able to increase the acetylation of α-tubulin in A549 cells by preventing the essential S-nitrosylation of HDAC6." (PMID 33020410, 2020). "Thus, the HDAC6-mediated deacetylation process might play a pivotal role in controlling breast cancer progression." (PMID 32106418, 2020). "It is indicated that an acetyltransferase CBP could regulate Sam68 acetylation, while histone deacetylase 6 (HDAC6) causes Sam68 deacetylation in cooperation with a nuclear matrix-associated protein, scaffold/matrix-associated region-binding protein 1 (SMAR1), in breast cancer." (PMID 32106418, 2020). "The log-rank P values were all less than 0.05, suggesting that patients with high expression of PAK1 and HDAC6/10 had higher mortality rates than those with low expression, indicating the potential of PAK1 and HDAC10 as therapeutic targets for breast cancer." (PMID 40302782, 2025). "First, we examined the levels of PAK1, HDAC6, and HDAC10 in breast cancer tissues at different disease stages." (PMID 40302782, 2025). "HDAC6 has been found to be overexpressed in a variety of malignant tumors, including acute myeloid leukemia (AML), colon cancer, and breast cancer." (PMID 38988323, 2024). "The overexpression of HDAC8 along with HDAC1 and HDAC6 has been shown to promote invasion of MDA-MB-231 and MCF-7 breast cancer cell lines." (PMID 38004560, 2023). "This study aimed to identify new dual inhibitors to combat one of the most aggressive types of breast cancer, TNBC, by considering two therapeutic targets: HDAC6 and Hsp90." (PMID 36838758, 2023). "Knockdown of HDAC6 increased the acetylation of heat-shock protein 5 (HSPA5) and reduced the ubiquitination and degradation of HSPA5 in breast cancer cells." (PMID 38093179, 2023). "Afterward, the cytotoxicity of HSB‐510 in breast cancer cell lines was evaluated and compared with the free PI3‐Kδ/HDAC6 inhibitor." (PMID 37693068, 2023). "Our results are pioneering concerning the evaluation of acetylated histones and deacetylase enzymes in bitches with simple mammary carcinomas and point to a relationship between high expression of HDAC1 and low HDAC6 with favorable prognostic factors." (PMID 38028583, 2023).
breast cancer (continued). "The downregulation of HDAC6 was reported to inhibit cancer stem cell (CSC) growth and autophagy and increase the apoptosis of breast cancer cells." (PMID 36076996, 2022). "Treatment TNBC and ERBB2+ breast cancer cells with neratinib also reduced the expression of p62 SQMT1, LAMP2, HDAC6, DRP-1, mitochondrial HSP70, HSP70, HSP90 and GRP78." (PMID 29163826, 2017). "In breast cancer cells, HDAC6 is a critical component of the invasive apparatus of tumor cells, and impacts epithelial organization of HER2-positive breast cancer cells." (PMID 29113288, 2017). "Deacetylation of heat-shock protein 5 (HSPA5) by histone deacetylase-6 (HDAC-6) is followed by Gp78-mediated ubiquitination of HSPA5, leading to suppression of invasion and migration in breast cancer cells." (PMID 28890687, 2017). "We found that chemotherapeutic agents or proteolytic stress in human breast cancer cells induced CDK1 degradation mediated by p62/LC3 and HDAC6." (PMID 28855742, 2017). "Herein, we demonstrate that both p62/HDAC6-dependent autophagy and the aggresome pathway mediate CDK1 clearance in human breast cancer." (PMID 28855742, 2017). "Notably, MDA-MB-231 cells displayed markedly decreased HDAC6 expression upon treatment, consistent with literature reports that TNBC exhibits elevated HDAC6 levels relative to other breast cancer subtypes." (PMID 41300448, 2025). "Our findings revealed that the levels of PAK1 and HDAC10 were elevated compared to those observed in individuals without breast cancer across various stages of the disease, while the expression level of HDAC6 displayed no significant change." (PMID 40302782, 2025). "In MCF-7 breast cancer cells, CBP-mediated acetylation and its effect on survivin deacetylation suggest that HDAC6’s subcellular localisation can be altered through interactions with acetyltransferase proteins and by regulating its binding with other protein partners." (PMID 39941046, 2025). "Similarly, hyperactivated ARID1A, phospho-HDAC6 and FOXM1 in Ewing’s sarcoma and breast cancer remodel chromatin structure via phase separation, driving oncogenic transcription and tumor progression." (PMID 40507965, 2025). "Besides, HDAC6 can also activate the phosphorylation of signal transducer and activator of transcription 3 on Tyr-705 and upregulate ZEB1 in MDA-MB-231 breast cancer cells to enhance EMT." (PMID 36457493, 2022). "The induction of HDAC6 may be correlated with high BCL2 levels and paclitaxel resistance in luminal breast cancer." (PMID 35453496, 2022). "Moreover, HDAC6 inhibition shows promise as an efficacious pharmaceutical intervention to alleviate CICD and improve quality of life of breast cancer survivors." (PMID 34976203, 2022). "Our study suggested that HDAC6 inhibitors can be used as therapeutic adjuvants of cysteine deprivation to treat various non-mesenchymal breast cancers." (PMID 34040090, 2021). "Furthermore, knockdown of HDAC6 in SKOV3 ovarian cancer, MCF7 breast cancer, and SKBR3 breast carcinoma cell lines reduced anchorage-independent growth to 3–20%." (PMID 30176876, 2018). "Importantly, WT161 with bortezomib overcomes bortezomib resistance in breast cancer cells; and HDAC6 inhibition by WT161 can enhance bortezomib-induced cytotoxicity by inhibiting both aggresome/autophagy pathway and UPR in breast cancer cells." (PMID 29113288, 2017). "To date, however, the biologic significance of HDAC6 in breast cancer has not been fully elucidated." (PMID 29113288, 2017). "HDAC6 also deacetylates HMGN2 to regulate STAT5a activity and breast cancer growth." (PMID 29113288, 2017). "Specifically, patients with HDAC6-positive breast cancer have longer progression-free survival and have increased overall survival after tamoxifen treatment, compared to patients with HDAC6-negative tumors." (PMID 29113288, 2017).
breast cancer (continued). "Therefore, it is not surprising to see that SAHA induced survivin acetylation and nuclear accumulation in MCF7 and MDA-MB-231 breast cancer cells in this study, given that SAHA is most potent in targeting HDAC6." (PMID 27065869, 2016). "Therefore, it is possible that inhibition of HDAC6 and HDAC3 all contributed to the SAHA induced survivin acetylation, nuclear translocation, and the subsequent protein degradation in breast cancer cells." (PMID 27065869, 2016). "Our study also reveals that down-regulation of survivin gene transcription and protein stability by the inhibition of HDAC6 and HDAC3 might play important roles in both SAHA-induced autophagy and SAHA-reduced cell viability in breast cancer cells." (PMID 27065869, 2016). "Upon HDAC6 inhibition by panobinostat, GRP78 is acetylated at 11 lysine residues, resulting in its dissociation from PERK and activation of a lethal unfolded protein response (UPR) in breast cancer cells." (PMID 27460191, 2016). "In breast cancer MCF-7 cells, HDAC6 helps lead to metastasis by up-regulating cell motility." (PMID 23644884, 2013). "HER2 may induce breast cancer by increasing the frequency of tumor stem cells and upregulating the expression of COX-2 and HDAC6 that play pivotal roles in tumor progression." (PMID 21044318, 2010). "Furthermore, paxillin knockdown in breast cancer cells was shown to disrupt Golgi complex localisation and cell reorganisation as a result of an increase in HDAC6 activity in the absence of paxillin." (PMID 39941046, 2025). "Studies have shown that tamoxifen-resistant T47D (T47D-TAR) cells are sensitive to HDAC6 inhibition by its effect on the Hippo pathway and inhibiting HDAC6 by suppressing YAP expression is considered a potential new strategy for treating tamoxifen-resistant breast cancer." (PMID 35449808, 2022). "Collectively, these results indicated that SAHA might promote survivin protein degradation in part through decreasing the ubiquitination protection from Hsp90 via HDAC6 inhibition and increasing the expression of 26S proteasome via HDAC3 inhibition in breast cancer cells." (PMID 27065869, 2016). "Studies employing siRNA targeting HDAC6 and LCOR indicated that HDAC6 may function with LCoR on some ERα target genes (such as IGFBP4, ADORA1 and CYP26B1) as part of a feedback loop to regulate estrogen-dependent gene regulation in breast cancer cells." (PMID 21814622, 2011). "It has been shown recently that HDAC6 may induce the expression of PD-L1 in cancer cells via the activation and recruitment of STAT3 transcription factors, as shown in experimental models of pharmacological impairment of HDAC6 or by its genetic abrogation in melanoma and breast cancer." (PMID 38258065, 2023). "Likewise, LiCl enhanced breast cancer cell motility; but the enhancement could be eliminated by knocking down FMOD, or individual components of the β-cat/TCF4/LEF1 transcriptional complex, or by inhibiting HDAC6 with Trichostatin A (TSA)." (PMID 31824307, 2019). "Since we have shown that HDAC6 selective inhibitor tubacin significantly enhances bortezomib-induced cytotoxicity in MM cell lines and patient MM cells, we examined whether WT161 or other HDAC inhibitors similarly enhanced anti-tumor activity of bortezomib in breast cancer cells." (PMID 29113288, 2017). "Therefore, quantitative real-time PCR was performed to determine whether HDAC2, HDAC3, and HDAC6 (but not HDAC1) can regulate survivin gene expression in breast cancer cells." (PMID 27065869, 2016). "In addition to the effects of LSD1 and HDAC6 on non-histone proteins, recent studies have shown that HDAC6, together with the CoREST complex, may play an important role in the estrogen receptor gene expression (ER) in breast cancer." (PMID 38004560, 2023). "Surprisingly, knock-down of HDAC6 did not demonstrate comparable biological effects, suggesting that the anti-proliferative activity of WT161 in breast cancer is not HDAC6 dependent." (PMID 29113288, 2017).
breast cancer (continued). "We identified and validated HDAC6 as a functionally necessary gene to maintain IBC cell viability, while being non-essential for other breast cancer subtypes." (PMID 26643555, 2015).